CST3 (cystatin C)
Diseases named in the same sentence as CST3 in open-access papers (continued):
Sharing a sentence is not in itself a finding about the gene and the disease.
Stroke (continued). "Cystatin C was significantly associated with stroke risk in our study." (PMID 37155257, 2023). "Moreover, regarding the clinical and biochemical variables, a higher level of hs-CRP, FBG, creatine, TC, TG, LDL-c, hemoglobin, uric acid, and cystatin C was positively associated with incident stroke." (PMID 35953770, 2022). "Furthermore, cystatin C-estimated glomerular filtration rate (eGFR) outperforms creatinine-based eGFR in predicting all-cause mortality in patients with ischemic stroke, consistent with our findings of elevated all-cause mortality in stroke patients with higher cystatin C levels." (PMID 40941489, 2025). "In addition, higher plasma cystatin C concentrations were associated with a higher risk of stroke." (PMID 37663661, 2023). "The H-FABP ≥ 0.2 ng/mL group showed higher SBP, prior stroke rate, and PA and also higher values in most of the cardio-specific biomarkers including CK-MB, NT-proBNP, TnI, myoglobin, cystatin-C and sST2 (p < 0.05)." (PMID 41010838, 2025). "Synthesizing the evidence from above, cystatin C serves as a pivotal biomarker for both stroke and cardiovascular mortality, driven by interconnected pathways such as atherosclerosis, inflammation, oxidative stress, and cardiac damage." (PMID 40941489, 2025). "Synaptosome‐derived EVs loaded with Cystatin C were capable of rescuing synaptic function in the ischemic penumbra, supporting the concept that EVs can preserve circuit integrity after stroke." (PMID 41287994, 2025). "This study elucidates the independent prognostic utility of serum cystatin C in predicting stroke morbidity and cardio-cerebrovascular mortality." (PMID 40941489, 2025). "Our findings show that cystatin C (CysC), a cysteine protease inhibitor expressed by all nucleated cells, is increased in synaptosomes isolated from mice at early time points after stroke." (PMID 38769196, 2024). "A multivariate logistic model and the two-sample Mendelian randomization framework were used to investigate the longitudinal and genetically predicted effect of serum cystatin C on stroke." (PMID 38681764, 2024). "In a cohort study, the significance of the relationships between cystatin C and stroke onset was switching when different cutoff values were used, which is partially due to over-adjusting." (PMID 38681764, 2024). "During a follow-up up to 7.0 years, 651 (10.0%) cases developed stroke events, and the incidence rates were 7.9%, 9.4%, 9.4%, and 13.2% among cystatin C quartile groups, respectively." (PMID 38681764, 2024). "The purpose of this research was to assess the longitudinal correlation between serum cystatin C concentration and new-onset stroke, using a national cohort." (PMID 38681764, 2024). "Our study supported the evidence that cystatin C is a predictor of new-onset stroke among Chinese adults, and the results were consistent after controlling for important risk factors." (PMID 38681764, 2024). "The use of B2M, cystatin C and LCN-2 as possible biomarkers allows the early identification of people with high stroke risk." (PMID 37155257, 2023). "Serum B2M, cystatin C and LCN-2 levels were significantly associated with stroke risk in the overall population (B2M: β = 0.595, p < .001; cystatin C: β = 3.718, p < .001; LCN-2: β = 0.564, p < .001) after adjustment for age." (PMID 37155257, 2023). "We aimed to investigate the relationship of B2M, cystatin C, and LCN-2 with stroke risk in a general Chinese population." (PMID 37155257, 2023). "We used ordinal regression to study the relationship between serum B2M, cystatin C, and LCN-2 with stroke risk in 1060 participants (mean age 45.4 ± 10.8 years, 46% male) from the Shenzhen-Hong Kong United Network on Cardiovascular Disease (SHUN-CVD) study." (PMID 37155257, 2023). "In this population-based study of adults aged above 18 years, we confirmed that there is a significant association of serum B2M, cystatin C and LCN-2 levels with stroke risk in a general Chinese population, even after adjusting for age." (PMID 37155257, 2023).
Stroke (continued). "Serum B2M, cystatin C and LCN-2 are significantly associated with stroke risk and are potential novel clinical biomarkers in the assessment of stroke risk." (PMID 37155257, 2023). "History of coronary disease, stroke, and hypertension showed a significant increasing trend with the cystatin C quintiles." (PMID 35453881, 2022). "All five markers showed associations with long-term risk of CVD (NT-proBNP, CRP, HbA1C and Cystatin-C for MI; GDF-15, NT-proBNP and CRP for stroke)." (PMID 34935094, 2022). "CST3 maintains blood-brain barrier integrity by regulating caveolin-1 expression after stroke in mice." (PMID 32733872, 2020). "Finally, to address some of the challenges of existing models, it might be valuable to consider addition of insight from biomarkers such as copeptin and serum asymmetric dimethylarginine (ADMA), cystatin C, Lipoprotein (a), all of which have shown some level of association with recurrent stroke." (PMID 31781015, 2019). "The subjects with higher grades of CMBs were more likely to have a previous history of stroke, higher cystatin C levels and more confluent white matter lesions." (PMID 24925313, 2014). "However, some variables that were significant in the main analysis (sleep quality, stroke, and creatinine) became non‐significant, while other strong predictors (depression, chronic lung disease, cystatin C) remained significant with similar effect sizes." (PMID 41473776, 2026). "Our findings demonstrate robust evidence supporting the role of serum cystatin C as an independent predictor of stroke morbidity after full adjustment for comorbidities (Model 3 OR = 1.27, 95% CI: 1.02–1.58), in line with previous observational and genetic studies." (PMID 40941489, 2025). "Increased cystatin C (CysC) levels after stroke may reflect lower glomerular filtration rate (GFR) and renal impairment." (PMID 38521825, 2024). "Moreover, there is existing evidence about the relationship between cystatin C and prognosis among stroke patients." (PMID 38681764, 2024). "A study among asymptomatic carotid atherosclerosis patients even claimed that cystatin C was significantly associated with subsequent cardiovascular events and stroke but not serum creatinine or estimated GFR." (PMID 38681764, 2024). "In contrast, other studies reported that cystatin C was not independently associated with ischemic stroke or any type of stroke." (PMID 38681764, 2024). "Contrary to what was found in a European population study, other studies have reported that cystatin C has no independent association with ischemic stroke or any type of stroke." (PMID 38681764, 2024). "A one-sample MR study using UK Biobank data reported that there is no causal association between cystatin C and stroke, which is opposite to the observational findings." (PMID 38681764, 2024). "In addition, cystatin C outperformed serum creatinine regarding the discrimination capacity of stroke." (PMID 38681764, 2024). "Moreover, it is reported that cystatin C is a possible determinant of endogenous neuroprotection and a protective factor against stroke in mechanism studies." (PMID 38681764, 2024). "Elevated serum B2M, cystatin C and LCN-2 levels are associated with stroke risk." (PMID 37155257, 2023). "Levels of B2M, cystatin C and LCN-2 among different strata of stroke risk factors." (PMID 37155257, 2023). "In this large-scale prospective cohort study, observational analysis found that each increase in plasma cystatin C concentration was associated with 9% higher risks of CVD events, 14% higher risks of CVD mortality, 10% higher risks of stroke, and 8% higher risks of MI." (PMID 37663661, 2023). "Therefore, there is a need to investigate the relationship between cystatin C and stroke in the general population." (PMID 37155257, 2023).
Stroke (continued). "On the other hand, increased cystatin C was suggested to be involved in endogenous neuroprotection, and exogenous cystatin C was found to exerte neuroprotective effects by reducing infarct volume in the animal stroke model." (PMID 35585568, 2022). "This suggests that the association between cystatin C and all-cause mortality in patients with stroke may follow a dose-dependent pattern, with no additional mortality risk observed beyond the threshold." (PMID 40941489, 2025). "Second, the NHANES database does not differentiate between the two primary stroke types (ischemic or hemorrhagic) or stroke subtypes, which may obscure etiology-specific cystatin C associations." (PMID 40941489, 2025). "The effects of cystatin C on subtypes of stroke could be distinct, which needs further elaboration." (PMID 38681764, 2024). "The Reasons for Geographic and Racial Differences in Stroke (REGARDS) cohort strongly suggested that the association of risk factors with stroke differed by race and sex, highlighting the need for validation regarding cystatin C and stroke on various races and populations." (PMID 38681764, 2024). "Only the association of cystatin-C with risk of stroke became non-significant." (PMID 34935094, 2022). "Previous studies have shown that malnutrition, Cystatin C, internal carotid artery occlusion, and brain atrophy can be used to assess the END of stroke patients." (PMID 40336946, 2025). "However, animal models have indicated that cystatin C may play a neuroprotective role in stroke." (PMID 37155257, 2023). "Positive associations reported previously between CAD, stroke, AAA, and DVT, with both cystatin C and red blood cell distribution width, as well as similar, atherosclerosis-based pathogenesis of CAD and stroke also support our observations." (PMID 32726343, 2020). "Cystatin C quartile distributions diverged substantially, with 62.43% of stroke cases concentrated in Q4 compared to 23.72% of non-cases (p < 0.001)." (PMID 40941489, 2025). "Hence, in clinical diagnosis and treatment, serum marker tests for A2M, LBP, CTSG, CST3, and FABP1 should be prioritized in patients with a high suspicion of stroke for early detection and timely intervention." (PMID 38090270, 2023). "A Mendelian randomization study using participant data from 16 prospective cohorts showed that cystatin C was not causally associated with CVD (RR: 1.00; 95% CI: 0.82, 1.22) and stroke (RR: 0.82; 95% CI: 0.57, 1.18)." (PMID 37155257, 2023). "Patients in the group with high cystatin-C values (>0.637 mg/L) had a significantly higher rate of MACCE (major adverse cardiac and cerebrovascular events, composed of CV death, ACS, stroke, and CHF hospitalization) after a 63-month median follow-up on multivariate analysis." (PMID 36676179, 2023). "stroke (cystatin C only) irrespective of the participant subgroup." (PMID 40082712, 2025). "Cystatin C-based eGFR may be useful for stratification of primary prevention decisions in stroke where stroke subtypes are not currently considered." (PMID 37641551, 2023). "We have previously reported that Cystatin C (CysC) is a pivotal mediator in the neuroprotection induced by hyperbaric oxygen (HBO) preconditioning; however, the underlying mechanism and how CysC changes after stroke are not clear." (PMID 30519802, 2019). "An acute phase reaction accompanying stroke or the stroke severity may influence the levels of cystatin C, though information about the changes in cystatin C levels after acute cardiovascular events has not been reported." (PMID 24925313, 2014). "Additionally, cystatin C activates inflammatory pathways (e.g., NF-κB) and promotes the release of pro-inflammatory cytokines (e.g., IL-6, CRP), establishing a vicious cycle of post-stroke neuroinflammation and delayed neuronal death, significantly increasing all-cause mortality." (PMID 40941489, 2025).
Stroke (continued). "Beta-2-microglobulin (B2M), cystatin C and lipocalin-2 (LCN-2) are established renal biomarkers, yet their roles in stroke have not been fully evaluated." (PMID 37155257, 2023).
heart failure (59 papers, 2009 to 2026). Inability of the heart to pump blood at an adequate rate to meet tissue metabolic requirements. "In high-risk populations, cystatin C consistently predicts adverse outcomes, including mortality, heart failure, and recurrent cardiovascular events, even after adjustment for traditional risk factors." (PMID 40941489, 2025). "Prior reports have revealed that basal Cystatin-C (CysC) is positively associated with all-cause death in patients with heart failure (HF)." (PMID 36148067, 2022). "Cystatin C was significantly associated with increased risk of heart failure in all three EV sub‐fractions and in plasma." (PMID 32648717, 2020). "Even more interestingly, we found that Cystatin C was associated with heart failure in all three sub‐fractions and in plasma as well." (PMID 32648717, 2020). "We also found a significant association of increased cystatin C levels and a higher hazard for hospitalization due to heart failure, as well as an independent association with higher mortality in heart failure." (PMID 32338126, 2020). "Elevated cystatin C, a marker of reduced kidney function, is associated with increased cardiovascular mortality and incident heart failure." (PMID 21977320, 2011). "In the Heart and Soul cohort with echocardiographic measures of LV structure in approximately 800 participants with coronary artery disease, cystatin C was associated with LV hypertrophy, diastolic dysfunction, and incident heart failure." (PMID 21977320, 2011). "The balance between cysteine proteases (cathepsins B, S, and K) and cysteine protease inhibitors (cystatin C) has been implicated in pathological LV remodeling in heart failure." (PMID 21977320, 2011). "In a recent report from the Physicians’ Health study, Djousse and co-workers demonstrated that higher levels of cystatin C were associated with an increased risk of heart failure and that this association was evident in hypertensive individuals only." (PMID 20676281, 2009). "During the last decade, several different indices reflecting renal function such as creatinine-based glomerular filtration rate, circulating levels of cystatin C and low-grade albuminuria have been demonstrated to be independent risk factors for heart failure." (PMID 20676281, 2009). "Cystatin C appears to be a superior marker for future risk of heart failure compared to serum levels of creatinine or creatinine-based equations of glomerular filtration rate." (PMID 20676281, 2009). "In fact, the population attributable risk of heart failure was 47% for blacks with moderate or high concentrations of cystatin C but only 5% in whites." (PMID 20676281, 2009). "In that study, the association between renal function and heart failure risk was stronger in older black individuals than in older white individuals, and this difference was particularly evident when cystatin C concentration was used to assess renal function." (PMID 20676281, 2009). "The association between serum cystatin C and development of heart failure in the community was first reported by Sarnak and co-workers in the Cardiovascular Health Study." (PMID 20676281, 2009). "In secondary analyses in the Cardiovascular Health study, slightly stronger associations between cystatin C levels and heart failure were seen in blacks as compared to whites." (PMID 20676281, 2009). "Weekley and Peralta indicated that combining creatinine, cystatin C, and albuminuria could improve the detection and risk stratification for heart failure and other cardiovascular events." (PMID 40053710, 2025). "Additionally, high concentrations of cystatin-C have been linked to greater risk of heart failure and death in persons with coronary heart disease (CHD)." (PMID 36963080, 2023). "How Cystatin C associates with risk of heart failure in patients with normal renal function remains unclear, but other reports suggest that again inflammation may an important linking mechanism." (PMID 32648717, 2020).
heart failure (continued). "This morphometric pattern of concentric LV remodeling may in part explain previously observed associations between cystatin C and diastolic dysfunction, heart failure, and cardiovascular mortality." (PMID 21977320, 2011). "In the present study, serum levels of IL-34 were found to be independently associated with renal biomarkers including eGFR and cystatin C among patients with HF, suggesting that IL-34 may play an important role in the process of heart failure mainly owing to its effect on renal function." (PMID 27982136, 2016). "Previous studies have shown that cystatin-C independently predicts mortality in patients with acute heart failure, even after adjusting for covariates such as BNP and heart failure risk factors." (PMID 41221210, 2025). "This research investigated the predictive value of combined detection of brain natriuretic peptide (BNP) and cystatin C (Cys C) in heart failure after percutaneous coronary intervention (PCI) in patients with acute myocardial infarction (AMI)." (PMID 37792781, 2023). "Previous prospective studies have reported that serum cystatin C concentrations are associated with the risk of coronary heart disease (CHD), myocardial infarction (MI), heart failure, and secondary cardiovascular events." (PMID 37663661, 2023). "A cohort study found that every SD increase in plasma cystatin C was found to be related to 22% higher risks of CVD mortality, 15% higher risks of all-cause mortality, and 27% higher risks of heart failure." (PMID 37663661, 2023). "Looking at differences between UHGL and ULGH groups defined by the clinical cutoff criteria, again significant associations (p < 0.001) were found for the variables age, male gender, heart failure, NTproBNP, and cystatin C." (PMID 34568379, 2021). "Previously, we reported that EV protein levels of Cystatin C, CD14, SerpinG1, and SerpinF2 were associated with heart failure in dyspnoeic patients." (PMID 32648717, 2020). "Recently, CKD outcome studies have established that cystatin C and albuminuria can improve risk stratification among persons with CKD defined by eGFRcr, with respect to mortality risk, cardiovascular disease, heart failure, and end stage renal disease." (PMID 26576434, 2015). "Several epidemiological studies showed that cystatin C is a better predictor of outcomes in coronary heart disease, acute coronary syndrome, and heart failure, independently of serum creatinine and GFR estimation." (PMID 25215234, 2014). "Taken together, the results indicate that estimated glomerular filtration rate and cystatin-C have similar long-term predictive values in a real-life ambulatory heart failure population." (PMID 23240006, 2012). "Cystatin-C seems to offer improved prognostication in heart failure patients with moderate renal dysfunction." (PMID 23240006, 2012). "Understanding the relationship between cystatin C and subclinical left ventricular (LV) remodeling, across ethnically diverse populations, may help explain the mechanisms underlying the association of kidney dysfunction with heart failure and cardiovascular mortality." (PMID 21977320, 2011). "In a report from the Heart and Soul Study involving ambulatory patients with coronary heart disease, higher cystatin C levels were found to predict incident heart failure." (PMID 20676281, 2009). "Serum cystatin C concentrations were associated with a linear increase in risk across quintiles of cystatin C, in contrast to serum creatinine concentration or estimated GFR where there was a J-shaped association with heart failure." (PMID 20676281, 2009). "Additionally, it has been reported that cystatin C is a predictor of long-term prognosis and rehospitalization in patients with heart failure and percutaneous coronary intervention." (PMID 37187794, 2023). "This supports the hypothesis that Cystatin C may be a marker for heart failure independently of renal function." (PMID 32648717, 2020).